KRAS (KRas proto-oncogene, GTPase)
Diseases named in the same sentence as KRAS in open-access papers (continued):
Sharing a sentence is not in itself a finding about the gene and the disease.
tumor (continued). "Overall, in our cohort of 6 metastatic CRC patients all harbouring KRAS mutations and none carrying BRAF mutations, 193 genes turned out to be significantly deregulated in the tumour compared to the paired stroma." (PMID 34439343, 2021). "It indicated that ADC can reflect expression of Ki-67 but no other relevant markers (tumor stages, grades and KRAS status)." (PMID 34109120, 2021). "TCR-redirected T cells display cytotoxic function against mKRAS tumor cell lines of various histologies without reactivity to wild-type (WT) KRAS peptides, thereby authenticating mKRAS G12V and G12R peptide ligands as bona fide neoantigens." (PMID 34272369, 2021). "Subsequently, we inquired whether KRAS is directly responsible for the production of CSF2 and lactate in tumor cells." (PMID 33833221, 2021). "Moreover, EMT can induce reduction in KRAS dependency of tumor cells (KRAS addiction) and different ZEB1 thresholds drive KRAS‐dependent tumor initiation and metastasis capacities." (PMID 34459003, 2021). "Taken together, our findings showed that RGS, a small molecular RAS signaling disruptor, had a selective anti-tumor effect and no obvious toxicity in KRAS mutant CRC." (PMID 34347396, 2021). "DDR1 is not important for tumor initiation, but it is critical in early tumor development and progression in KRAS (Ki-ras2 Kirsten rat sarcoma viral oncogene homolog)-driven lung adenocarcinoma." (PMID 33917302, 2021). "KRAS-mediated repression of interferon regulatory factor 2 (IRF) results in the high expression of the chemokine C-X-C motif ligand 3 (CXCL3), which induces MDSCs that express C-X-C motif chemokine receptor 2 (CXCR2) as the receptor of CXCL3 in tumor tissues." (PMID 34359568, 2021). "However, unlike in our study, they did not provide the QALY gained and ICER of anti-EGFR mAb compared to Bev in different scenarios of KRAS WT, pan-RAS WT, and pan-RAS left-sided tumor population to justify their conclusion." (PMID 34012917, 2021). "Neither mutations in KRAS or PI3CKA, nor the levels of COX-2 expression at the time of resection of the residual tumor were predictive of these aspirin benefits." (PMID 33430037, 2021). "Ferroptotic cancer cells can release and activate distinct signals including DAMPs (e.g., HMGB1, KRAS-G12D, and 8-OHG) or oxidized lipid mediators (e.g., 4HNE, oxPLs, LTB4, LTC4, LTD4, and PGE2) that may modulate inflammatory and anti-tumor immunity." (PMID 34796174, 2021). "We suggest that IL-17A rs8193036 SNP might affect LUAD tumor progression and its clinical course in patients harboring the WT EGFR and MT KRAS." (PMID 33802737, 2021). "In addition, our data on the Fusobacteria relationship with the tumor molecular characteristics of MSI and KRAS/NRAS/BRAF status were consistent with studies using frozen tissue specimens and another study with FFPE tissue specimens." (PMID 34650531, 2021). "However, BRAF selective inhibitors are effective only in BRAF mutant tumor models and have paradoxically activated ERK signaling in KRAS mutant or RAS/RAF wild type tumor models." (PMID 34805167, 2021). "Patient characteristics, including age, gender, pack-years, race, tumor site, epithelial growth factor receptor (EGFR) status, anaplastic lymphoma kinase (ALK) status, kirsten rat sarcoma viral oncogene (KRAS) status, TNM stage, pathological stage, and gene expression, were collected." (PMID 33686947, 2021). "Our model demonstrated that anti-EGFR therapy is cost-effective compared to Bev in pan-RAS WT in particular left-sided tumor, but not KRAS WT population." (PMID 34012917, 2021). "Given the importance of developing better treatments for patients with KRAS driven tumours, non-toxic combinations with VitC are also being explored and will be discussed in the following section." (PMID 34717701, 2021).
tumor (continued). "The ablation of CRAF in advanced tumours driven by KRAS oncogene leads to significant tumour regression with no detectable appearance of resistance mechanisms and limited toxicities." (PMID 34103645, 2021). "In elderly HGSOC, mutations in the genes that are involved in the Ras and or PIK3CA signaling pathways were detected in nine samples (15%), including the genes KRAS and BRAF (each one in 1 tumor); PIK3CB and MTOR (each one in 2 tumors); and NF1 (in three different samples)." (PMID 34944094, 2021). "Further, in mutant KRAS driven NSCLC inhibition of PI3K-mTOR did not reduce tumor growth substantially but inhibition of cRAF, another effector of KRAS, decreased cancer progression." (PMID 34805167, 2021). "The ability of voruciclib to inhibit tumor growth in vivo was also tested in murine xenograft models injected separately with KRAS mutant CRC, NSCLC primary human cancer cells, wherein significant tumor growth inhibition (>50%) was observed at all doses of voruciclib." (PMID 34944853, 2021). "We also investigated whether BLT2 inhibition could suppress tumor formation and IL-6 production in these mice and observed that treatment with LY255283 clearly suppressed KRAS-driven lung tumor formation and IL-6 production." (PMID 34635780, 2021). "A phase Ib/II trial evaluating the anti PD-L1 monoclonal antibody avelumab combined with the MEK1/2 inhibitor binimetinib, with or without the PARP inhibitor talazoparib (NCT03637491), including patients with advanced, KRAS + NSCLC, showed limited anti-tumor activity with a high toxicity." (PMID 34944952, 2021). "For example, expression of BrafV600E accelerated KRAS KO tumor development in nude mice twofold, but had no discernible effect in wild-type mice." (PMID 33674596, 2021). "Besides, the alterations of AOX15, KRAS, and PGD mainly focused on domain lipoxygenase, Ras, and 6PGD, indicating that these domains played a crucial role in ferroptosis and tumor progression." (PMID 34434214, 2021). "In NSCLC mouse models, it has been found by various studies that CRaf was required for proper tumor initiation but not BRaf, as total ablation of BRaf but not CRaf allowed oncogenesis in KRas G12D and G12V mutant mice." (PMID 34680208, 2021). "Moreover, RGS treatment disrupted RAS/MEK/ERK and PI3K/AKT signaling in KRAS-mutant CRC cell lines and KRAS-mutant PDX tumor specimens." (PMID 34347396, 2021). "Notably, JAB-3312 can block the PD-1 pathway of T cells and the KRAS-MAPK pathway of tumour cells by inhibiting SHP2; thus, it plays a dual role in tumour immunity and tumour targeting." (PMID 34012925, 2021). "Through analyses of a variety of human KRAS, NRAS or BRAF mutant cell lines from different tumor entities (CRC, NSCLC, PDAC, RMS) we further showed that these principles also apply to the complex genetic backgrounds that arise during human RAS-pathway driven cancer development." (PMID 33924486, 2021). "Recently, it has been shown that the addition of Vitamin C in pharmacologic concentrations selectively kills KRAS mutant cells, resulting in the downregulation of both GLUT1- and PKM2-dependent protein expression, suggesting its positive role in anti-tumour therapies." (PMID 33925206, 2021).
tumor (continued). "KRAS mainly activates the PI3K/AKT/mTOR and BRAF/MEK/ERK pathways and activates inflammatory pathways such as the NFκB signaling pathway, which is required for tumor maintenance and malignant transformation." (PMID 34336638, 2021). "KRAS signaling induces the expression of immune regulatory factors and inflammatory cytokines in tumor cells, and subsequently recruits neutrophils and myeloid-derived suppressor cells (MDSC) to form an immunosuppressive tumor microenvironment." (PMID 34616403, 2021). "The signaling cascades downstream of the KRAS protein leading to the following pathways involving RAF/MAPK/ERK, PI3K/AKT, and RAL GDS/RAL have been well elucidated and are considered to differ according to the tumor type." (PMID 33982211, 2021). "Irrespective of which T-cell population was eliminated, tumor protection was lost as these mice developed KRAS KO tumors in a timeframe similar to that in nude mice." (PMID 33674596, 2021). "In contrast, KRAS depletion experiments in human models began to separate tumor cells with KRAS dependency from those lacking this reliance." (PMID 34680229, 2021). "However, for the KRASG12C tumor, LINCS analysis returned different drugs (NES < −3.6, P < 0.04), inhibitors of HSP70, GSK3β, and KRAS signal transducers BRAF and RAF1." (PMID 33712615, 2021). "Recent evidence has been provided that KRAS mutation assessment in NSCLC baseline plasma samples is feasible, especially in patients in whom tumor tissue is not available for molecular testing." (PMID 34943432, 2021). "Edema Tumor Volume ratio on the other hand, was significantly associated with survival duration in the EGFR and KRAS mutation-positive groups, but not in ALK mutation-positive group." (PMID 33747933, 2021). "Thirdly, we did not carry out subgroup analyses according to tumor stage, oncogenic alteration (e.g., EGFR mutation, EML4-ALK fusion, KRAS mutation), expression status of PD-1/PD-L1, etc. due to the limitations of the data." (PMID 34497760, 2021). "Critically, CCT3833 mediates tumor regression in G12SKRAS-mutant NSCLC xenografts, so it could be considered for treatment of KRAS-mutant NSCLC patients who fail chemotherapy and/or immunotherapy." (PMID 33130216, 2021). "Accumulating evidence supports the pivotal role of KRAS not only in governing cancer cells’ autonomous mechanisms of proliferation, but also in controlling the immune landscape within the TME and in mediating immune escape and ultimately tumor progression." (PMID 33494181, 2021). "Tumours with KRAS G12C showed a lower TMB than those with non-KRAS G12C mutations (12 vs. 20.5 muts/Mb, p < 0.05)." (PMID 33889543, 2021). "Finally, mutant KRAS silencing led to increased expression of MHC I surface proteins on tumor cells and production of IL-18, inducing ultimately tumor regression." (PMID 33494181, 2021). "In KRAS-mutant cancer, whether G12 or G13, BI-3406 decreased the KRAS-GTP level and restricted the proliferation of the majority of tumor cells." (PMID 34742312, 2021). "If the expression of oncogenic KRAS transgenes is silenced during pancreas development and only activated in adult animals, neither PanIN development nor tumor will develop." (PMID 34046348, 2021). "While MRTX1257 is a tumour-specific inhibitor, acting only on the G12C mutant form of KRAS protein found in the tumour cells and not the wild-type KRAS protein found in the cells of normal tissue, it had profound indirect effects on the TME." (PMID 34625563, 2021). "Consistent with previous reports, none of our AA ESCC tumor samples that displayed amplified mutant EGFR showed wild type KRAS amplification." (PMID 34285259, 2021).
tumor (continued). "The current results revealed the KRas engagement of NSC290956 in intact cells by thermally stabilizing KRas, further blocking the cellular KRas activity and resulting in a degree of KRas-dependent lethality in NSCLC tumor cells." (PMID 35069209, 2021). "The tumour size and neutrophil infiltration in these models of SIK1/3 disruption were comparable to those seen when LKB1 was knocked out alongside the expression of KRAS[Gly12Asp]." (PMID 33861845, 2021). "This was seen clinically when a patient with KRas mutant NSCLC was treated with vemurafenib and showed signs of a tumor flare indicative of paradoxical activation that may occur when weakly inhibiting Raf kinases." (PMID 34680208, 2021). "Analyzing the whole-blood expression signature of four growth factor-related genes (ARAF, BRAF, KRAS, and RAF-1) and four genes involved in metabolism (ATP6V1H, OAZ2, PANK2, and PLD3), combined with tumor grade, they were able to predict the efficacy of PRRT with an accuracy of 95%." (PMID 33809226, 2021). "Third, a large proportion of the patients treated with bevacizumab were mutant for KRAS/RAS, and this might have affected our analysis, especially the comparison of efficacy between left- and right-sided tumours." (PMID 33188279, 2020). "Here, we present evidence that KRAS-driven TICs have increased IKKβ kinase activity, which, not only promotes stemness, but is also involved in tumour cell migration and invasion." (PMID 32823550, 2020). "Apart from the common cancer types, sintilimab was involved in suppressing tumor progression on a KRAS positive patient with hepatoid adenocarcinoma (HAC), a sort of rare tumor secreting AFP with morphological similarities to HCC, and eventually achieved a 52-month OS." (PMID 33292551, 2020). "Both the patients with KRAS positive vs. KRAS negative primary tumor tissue experienced similar DMFS (median 210 vs. 186 days, p = 0.215)." (PMID 32867151, 2020). "Retrospective studies and prospective clinical trials evaluating the effect of statins on patients stratified by tumour location and KRAS status are lacking." (PMID 32594310, 2020). "Candidate pathogenic mutations in untranslated regions (UTRs) and BC-relevant genes regions, including oncogenes (i.e., KRAS, ERBB3, PIK3C2G) and tumor suppressor genes (i.e., FANCC, ATR, SMAD2), were found in organoids, and the majority of them were conserved within the tumor–organoid pair." (PMID 33371412, 2020). "The percentage increment of KRAS fractional abundance in primary tumor tissue (tFA) did not influence patients ́ DMFS (HR 0.989, p = 0.185)." (PMID 32867151, 2020). "However, new discoveries about KRAS biology and its impact in the tumor microenvironment, together with the advent of immunotherapies and targeted therapies, may result in the development of effective treatment strategies and optimal therapeutic stratification of KRAS-mutant LA." (PMID 32714871, 2020). "The therapeutic ablation of these secondary targets would hypothetically result in the selective death of KRAS-mutant but not KRAS wild type tumor cells." (PMID 32548736, 2020). "KRAS/STK11 NSCLC (25% of KRAS+ NSCLC) lacked tumor-infiltrating lymphocytes and expressed reduced levels of immune markers and PD-L1." (PMID 32560574, 2020). "Finally, we focused on patient 21, with a pT3N0 intestinal histologic subtype tumor arising from the gastric antrum characterized by gains of EGFR, MYC (OMIM 190080) KRAS, MET, and PIK3CA by OncoScan (eFigure 4C in the Supplement)." (PMID 32338752, 2020).
tumor (continued). "Likewise, Bcl-2, PTEN, KRAS, and BRAF are the genes that regulate apoptosis, acting as an important signaling molecule of their downstream pathway involved in the formation of tumor resistance." (PMID 32695666, 2020). "From 1979, cellular ras sequences with transforming properties were identified by transfection of tumor DNA initially by Robert Weinberg from rodent tumors, and the isolation of homologous oncogenes from human tumors soon followed, including HRAS and KRAS, and a new member of the family named NRAS." (PMID 32728828, 2020). "Unfortunately, we were not able to provide matched tumor tissue KRAS analysis using ddPCR in these samples, due to inadequate FFPE tissue specimens." (PMID 33233668, 2020). "Consistently, dCas9-KRAB-sgG12S, but not LentiCas9-vector, treated tumor tissues exhibited markedly lower levels of both total and mutant KRAS proteins in A549-engrafted mice." (PMID 32308773, 2020). "The treatment of Cas9-sgG12S in A549 tumor cells dramatically suppressed the expression of the KRAS (G12S) protein, while the expression of wild- type KRAS protein in H2228 cells were not affected." (PMID 32308773, 2020). "We tested the independence of ABCG2/TOP1 status in multivariable models including tumor site, MSI status, mucinous histology, and BRAF and KRAS mutation status (without interaction terms)." (PMID 32326511, 2020). "Functionally, the phosphorylation of KRas-4B can have either a negative or positive regulatory effect on tumor cell growth, depending on the conditions." (PMID 33266473, 2020). "It has been demonstrated that anti-EGFR antibody treatment with cetuximab and with panitumumab did not confer benefits for tumours with a mutant KRAS gene." (PMID 33183271, 2020). "In general, squamous patients with NSCLC bear a heavier tumor mutational burden with exception of targetable genomic mutations (e.g., EGFR, KRAS, or ROS1) than nonsquamous patients with NSCLC." (PMID 31693178, 2020). "KRAS was suggested as a biomarker for treatment with AZD6244 (Selumetinib), which is a MEK1 inhibitor, while another phase II clinical study identified that NF1 was also indicative of tumor response to AZD6244." (PMID 32604779, 2020). "In both discrepant cases the primary tumor harbored a KRAS mutation, thus the patients were initially stratified to receive no EGFR-antibody therapy because of the presence of a KRAS mutation." (PMID 33002027, 2020). "In the present study, we evaluated associations between clinical, metabolic and molecular parameters (KRAS status) in metastatic CRC (mCRC) patients according to a novel classification for primary tumour location." (PMID 32594310, 2020). "There are no drugs that target most KRAS mutant proteins, and these tumours respond poorly to chemotherapies." (PMID 32326637, 2020). "Moreover, we detected 15 gene amplifications in six different tumor specimens, including AR, CCND1 (n = 2), FGF19 (n = 2), FGF3 (n =2), KRAS (n = 2), MYC (n = 2), CCND3, CCNE1, CDK6, and RICTOR." (PMID 33203166, 2020). "Of note, right-sided tumor location alone was attributed to shorter survival-after-recurrence and OS independent of the KRAS status." (PMID 32707813, 2020).